CCND1 (cyclin D1)
Diseases named in the same sentence as CCND1 in open-access papers (continued):
Sharing a sentence is not in itself a finding about the gene and the disease.
breast cancer (continued). "Thirdly, we found that KO of Kdm3a in the mammary tumor cells decreased cyclin D1 expression and tumor cell proliferation, suggesting that Kdm3a also up regulates cyclin D1 expression and promotes cell proliferation in breast cancer cells." (PMID 29156681, 2017). "Breast epithelial cell cyclin D1 protein overexpression is found in up to 50% of human breast cancers." (PMID 29137220, 2017). "Many previous studies focusing on ER-positive breast cancer have found high cyclin D1 expression or gene amplification to be an adverse prognostic sign, while the results in ER-negative and in unselected breast cancer patients have been highly inconsistent." (PMID 28528450, 2017). "To investigate the role of Kdm3a in modifying cyclin D1 expression in the mammary tumor cells, we measured cyclin D1 mRNA and protein expression by real-time polymerase chain reaction (QPCR) and IHC." (PMID 29156681, 2017). "The current studies provide evidence for the independent prognostic significance of stromal cyclin D1 and suggest consideration be given to evaluation of cyclin D1 in the stroma of breast cancer when considering patient prognosis." (PMID 29137220, 2017). "Immunoblotting results identifying the suppression of miR-129 exerted on ESR1 and its downstream cyclin d1 in breast cancer stem-like cells." (PMID 29262559, 2017). "In contrast breast cancer cell lines overexpressing cyclin D1 showed enhanced apoptosis in response to γ irradiation suggesting cell type specific differences governing cyclin D1 mediated apoptosis." (PMID 29137223, 2017). "Hydroxylation of FOXO3a by PHD1 has been shown to regulate cyclin D1 transcription, representing a potential mechanism by which PHD1 loss in breast cancer can impair cell growth." (PMID 28536364, 2017). "The finding that the stromal cyclin D1 increases breast cancer autophagy contrasts with the cell autonomous function of cyclin D1 in tissue mono culture, wherein cyclin D1 restrains epithelial cells and fibroblast autophagy via phosphorylation of LKB1." (PMID 29137220, 2017). "Slug can induce elevation of cyclin D1 in breast cancer cells, which is an important mediator of both tamoxifen resistance and MDR." (PMID 28334049, 2017). "The abundance of cyclin D1 is rate limiting in the growth of tumors in vivo, including ErbB2-induced breast cancer and gastrointestinal tumorigenesis." (PMID 29137220, 2017). "This, together with the finding that CCND1 amplification is usually homogeneous within breast carcinomas, suggests that it is an early event in the development of some breast cancers." (PMID 28095868, 2017). "Studies also revealed that wogonin induces apoptosis through the modulation of apoptotic factors and induces change of cell cycling by regulation of the cyclin D1 expression in human breast cancer." (PMID 29181409, 2017). "Knockdown of PAK5 inhibited human breast cancer cell proliferation by inducing cell cycle arrest in G0/G1 phase, which is generally in concordance with the downregulation of Cyclin D1." (PMID 29041983, 2017). "Dysregulation of the CDK4/6- cyclin D1 complex is an important step in the genesis of breast cancer, and several genetic alterations in cell cycle regulatory proteins have been described." (PMID 29140993, 2017). "The current studies demonstrate that cyclin D1 mRNA abundance is increased 30-fold in the stroma of patients with breast cancer." (PMID 29137220, 2017). "Our data provide important insight into the PAK5-p65 signals in regulating Cyclin D1 to promote breast cancer growth." (PMID 29041983, 2017). "A transcriptional enhancer in the G allele of rs554219 increases the risk of breast cancer by reducing the binding of ELK4 transcription factor and correlates with low cyclin D1 levels in breast cancer tissues." (PMID 29299175, 2017). "Prior studies had assessed the prognostic significance of nuclear cyclin D1 abundance in the breast cancer epithelial cell." (PMID 29137220, 2017).
breast cancer (continued). "Cyclin D1 amplification or overexpression however identified a subset of ERα+ breast cancers with worse prognosis, suggesting additional interactions modify cyclin D1 function." (PMID 29137220, 2017). "Others have reported that overexpression of AP-2α inhibits breast cancer cell growth by inducing the expression of the cell cycle inhibitor p21, repressing cyclin D1, decreasing Rb phosphorylation, and by enhancing E2F activity." (PMID 29100274, 2017). "Since EYA1 was reported to increase cyclin D1 production and decrease phosphorylated γH2AX in breast cancer cells, we examined if these were the case in melanoma cells." (PMID 29285235, 2017). "The prognostic and predictive value of cyclin D1 overexpression in breast cancer remains controversial." (PMID 29140993, 2017). "PRKCB was reported to enhance the expression of cyclin D1 in human breast cancer cells, leading to cell proliferation and cell cycle progression." (PMID 28422739, 2017). "Cyclin D1 dysregulation in human breast cancer cells in vitro promotes progression to G1⁄S transition, with loss of growth control, decreasing the dependence of these cells on growth factors." (PMID 29140993, 2017). "Cyclin D1 is overexpressed in more than 50% of breast cancers, functioning as a rate-limiting factor for human breast cancer cell proliferation in vivo and in vitro." (PMID 28212313, 2017). "Jak/STAT3, ERK1/2, phosphoinositide 3-kinase pathways and cyclin D1 expression pathways are reported to be involved in mediating leptin-stimulated breast cancer cell growth." (PMID 28930270, 2017). "The clear up-regulation of CCND1 after Roniciclib treat﻿ment ﻿in addition to the decrease in the protein levels of c-Myc were recapitulated by Western blotting of MCF7 breast cancer cells, suggesting a common mechanism across tissue types." (PMID 28246384, 2017). "The growth of hormone receptor–positive breast cancer is dependent on cyclin D1, which is a direct transcriptional target of the estrogen receptor." (PMID 29928547, 2017). "Overexpression of miR-17-5p inhibits hormone-dependent breast cancer cell proliferation by targeting AIB1 or cyclin D1." (PMID 29126392, 2017). "The possibility the hypoxia induces degradation of Cav-1 and consequently induces cyclin D1 in the breast cancer stroma remains to be investigated." (PMID 29137220, 2017). "Nine genes in this module – Akt1, Brca2, Ccnd1, Dnmt1, Mki67, Palb2, Rrm1, Timeless, and Top2a – are known human breast cancer genes according to the MalaCards database; four of them are hub genes." (PMID 28212608, 2017). "The aim of this study was to further explore the prognostic effect of cyclin D1 aberrations in relation to ER status in a patient material designed for evaluation of prognostic factors in early breast cancer." (PMID 28528450, 2017). "Cyclin D1 enhances breast cancer cellular proliferation in vivo and endogenous cyclin D1 maintains estradiol-mediated mammary epithelial cell gene expression in vivo." (PMID 29137220, 2017). "The expressions of β-catenin and cyclin D1 were also compared in breast cancer patients with different hormone receptor statuses." (PMID 28533512, 2017). "Cyclin D1 selectively inhibits ligand-dependent AR function in several cell types, including breast cancer, bladder cancer, and androgen-independent prostate adenocarcinoma cell lines." (PMID 29137223, 2017).
breast cancer (continued). "We found that PSAT1 regulates the expression of cyclin D1, which is an important regulator of G1 to S phase in a variety of cancers, including breast cancer, to promote cell cycle progression." (PMID 29216929, 2017). "The proliferation of MDA-MB-231 cells was increased approximately 65% at 72 hrs by cyclin D1Stroma suggesting stromal cyclin D1 participates in heterocellular signals to the breast cancer cells (p-value = 0.004)." (PMID 29137220, 2017). "Then, p65 bound to Cyclin D1 promoter and facilitated breast cancer cell proliferation in vitro as well as in vivo." (PMID 29041983, 2017). "A ribozyme against HuR decreased HuR expressions and inhibited breast cancer cell growth and invasion with a concomitant reduction in the levels of cyclin D1." (PMID 28968471, 2017). "TransATAC is by far the largest published study of cyclin D1 signaling and breast cancer prognosis (n = 1155)." (PMID 28528450, 2017). "Taken together, PAK5 can augment the expression of Cyclin D1 and Cyclin D3 and inhibit the expression of p21 and p27, accelerating cell-cycle progression in breast cancer cells." (PMID 29041983, 2017). "Taken together, these findings clearly demonstrate that autophagy targets and degrades E2F1, thereby leading to cyclin D1 induction in leptin-treated MCF-7 breast cancer cells." (PMID 29312618, 2017). "Specifically, the miR-17-5p cluster acts as a tumor suppressor by directly inhibiting the expression of AIB1 and cyclin D1 in human breast cancer." (PMID 28178652, 2017). "For example, resistance to tamoxifen has been associated with constitutive activation of MAPK and the subsequent expression of cyclin D1 in FGFR1-amplified breast cancer cell lines." (PMID 28183331, 2017). "A large number of previous studies have investigated the prognostic impact of cyclin D1 expression or gene amplification in primary breast cancer." (PMID 28528450, 2017). "Cyclin D1 protein expression has been reported to be a prognostic marker in breast carcinoma, and most studies have shown that overexpression is a good prognostic factor, particularly for ER-positive patients." (PMID 29140993, 2017). "Detection of overexpression of cyclin D1 by immunohistochemistry has been reported in 35–81% of breast carcinomas, in line with our results." (PMID 29140993, 2017). "CCND1-amplified tumors are a separate entity within RE+, Luminal B subtype and high-grade breast carcinomas, with shorter DFS and poor outcome." (PMID 29140993, 2017). "Cyclin D1 overexpression showed a correlation with longer survival in breast carcinoma and colorectal cancer." (PMID 28069005, 2017). "Our results suggest that MST3/VAV2/cyclin D1 is one of the important oncogenic pathways in breast cancer development, but breast cancer development requires a coordination of MST3 pathway and other oncogenic pathways." (PMID 26910843, 2016). "Cyclin D1 is probably the most frequently overexpressed gene in primary breast cancer (approximately 15% of breast cancer patients)." (PMID 27990275, 2016). "High-level coexpression of MST3 and cyclin D1 was observed in human breast cancer and was correlated with poor overall survival by using the Kaplan-Meier plotter." (PMID 26910843, 2016). "This is consistent with in vitro and in vivo studies showing a deregulation of the G1/S transition after downregulation of Per2 in murine breast cancer cells, and cyclin D1-dependent cell cycle deregulation in Per2-/- mice models." (PMID 26741371, 2016). "In this study, we demonstrated that miR-193a-3p suppressed breast cancer cell growth by directly inhibiting CCND1, PLAU and SEPN1 expression, and suppressed breast cancer cell migration/invasion via silencing PLAU." (PMID 27307030, 2016).
breast cancer (continued). "A stimulatory effect on cyclin D1 protein expression was also shown in breast cancer, endometrial cancer and colon cancer cells and in hepatocellular carcinoma." (PMID 27480179, 2016). "Nevertheless, amplification of CDK4 and cyclin D1 have been reported in upwards of 15–25 % of breast cancers, while overexpression of cyclin D1 has been reported to occur in over half of all breast cancers in some published studies." (PMID 26857361, 2016). "InuA upregulated the expression of p21 and Bax, induced the cleavage of PARP, and reduced the expression of Cdk2, Cdk4, Cdk6, Cyclin D1, Cyclin E, c-Myc, and Bcl2 in both breast cancer cell lines." (PMID 27105525, 2016). "In contrast, EYA1 induces cyclin D1 through its phosphatase activity in breast cancer, and SIX1 directly enhances the transcription of cyclin D1 in rhabdomyosarcoma tumor cells." (PMID 27203207, 2016). "Further evidence for their role in malignant pathogenesis derives from studies demonstrating that the cyclin D1:CDK4/6 axis is critical for breast cancer maintenance and progression." (PMID 26857361, 2016). "In the breast cancer cases, the oncogene CCND1 was gained more frequently in the IDC samples than in the DCIS samples, but again the difference was not significant (p < 0.23)." (PMID 27362268, 2016). "Our results demonstrate a novel tumor suppressor role for miR-1296 in triple-negative breast cancer cell lines, identify CCND1 as its target of action, and demonstrate a potential role for miR-1296 in sensitizing breast cancer cells to cisplatin." (PMID 26799586, 2016). "For example, silencing of cyclin D1 increases the migratory capacity of MDA-MB-231 breast cancer cells." (PMID 27385093, 2016). "Among the six copy number alterations assayed, the CCND1 alteration was detected as the most frequent one, existing in 16% of breast cancer cases." (PMID 27190992, 2016). "Evidence indicates that dysregulation of the cyclin D1:CDK4/6 axis has a role in breast cancer, with some tumors overexpressing cyclin D1." (PMID 26857361, 2016). "In this study, we observed that inhibition of miR-203 in ER-positive breast cancer cells suppresses cell proliferation by inhibiting cyclin D1 and pStat3, and inhibits tumor growth in a breast cancer preclinical model." (PMID 27517632, 2016). "The proto-oncogene protein cyclin D1 is overexpressed in a variety of cancers, including colon cancer, breast cancer, and lung cancer etc. to advance cell cycle progression from G1 phase to S phase." (PMID 27504094, 2016). "Cyclin D1 expression was efficiently depleted by siRNA in cells derived from liver cancer (HepG2) and breast cancer (MCF7), which resulted in decreased DNA synthesis and cell proliferation." (PMID 27351284, 2016). "For example, we reported amplification of CCND1 in two breast cancers and the CNA calls were supported by CCND1 gene expression analysis." (PMID 27245685, 2016). "Our in vitro data suggested that cyclin D1 expression was inhibited in miR-203 knockdown breast cancer cells as compared with control cells." (PMID 27517632, 2016). "Leptin promoted cell proliferation and homotypic tumor cell adhesion through increased expression of E-cadherin and cyclin D1 in vivo in breast cancer xenograft and in vitro in breast cancer cell lines." (PMID 27185268, 2016). "ATO is an antagonist of CCND1, which has been validated in many cancers, such as bladder cancer, breast cancer, kidney cancer, liver cancer and NSCLC." (PMID 26655252, 2016). "When analyzed by intrinsic subtype of breast cancer, alterations in cell cycle genes varied, with cyclin D1 amplification being found most frequently in the luminal A, B and HER2 enriched subtypes at frequencies of 29 %, 58 %, and 38 %, respectively." (PMID 26857361, 2016). "Collectively, these findings suggested that anti-miR-203 decreased the proliferation of breast cancer cells by inhibiting cyclin D1 and enhancing p21 expression." (PMID 27517632, 2016).
breast cancer (continued). "In one study where two single breast cancer CTCs per patient were analyzed for CNA, all CTCs displayed a typical breast cancer related copy number profile, with six patients harboring CCND1 amplification in both CTCs." (PMID 26980749, 2016). "CCND1 is a well-known oncogene (the function enhancement of the gene will lead to tumors) that has been found to be amplified in breast cancer and head and neck carcinoma." (PMID 27148394, 2016). "On the gene level, in addition to TGFBR2 and CCND1, IL5 and GM-CSF showed the strongest associations with overall breast cancer risk (p value = 1.0 × 10−3 and 7.0 × 10−3, respectively)." (PMID 26621531, 2016). "One of the predicted targets, CCND1, has already been validated as a target of miR-503 and the repression of CCND1 by miR-503 has been reported to inhibit proliferation in breast cancer cell lines." (PMID 27539783, 2016). "It has been reported that over-expression of cyclin D1 promoted breast cancer cells (MDA-MB-236) and lung cancer cells (A549) proliferation." (PMID 26909600, 2016). "The ERα protein is a well-known positive regulator of cyclin D1 and c-Myc, two important apoptosis modulators in breast cancer cells." (PMID 27465411, 2016). "Our previous studies showed FOXC1 increases expression of Cyclin D1, phosph-P65 and P65 in breast cancer cells." (PMID 27533251, 2016). "ATF2 has been reported to modify Cyclin B1 and Cyclin D1 levels to promote cell-cycle progression in several types of neoplasms, including cervical and breast cancer." (PMID 27377902, 2016). "For example, we observed a dramatic increase in R-loops at Cyclin D1, which is amplified in up to 20% of breast cancers, the majority of which are ER-positive." (PMID 27552054, 2016). "In the present study, knockdown of FOXM1 led to a marked reduction in cyclin D1 expression, which was recently shown to be regulated by eEF2K in breast cancer cells." (PMID 26918606, 2016). "It controls focal adhesion and androgen-related cell migration in human fibrosarcoma and Cyclin D1/cyclin-dependent kinase 4 mediated cell migration in breast cancer." (PMID 27124473, 2016). "In liver and breast cancer cells, knockdown of cyclin D1 leads to increased PPARα transcriptional activity, expression of PPARα target genes, and fatty acid oxidation." (PMID 27351284, 2016). "Further, EZH2 KD was shown to induce a G2/M arrest in breast cancer and regulated cyclin D1, and β-catenin." (PMID 27092879, 2016). "It has been reported that SIX1 showed great influence on cell proliferation, survival, and motility by transcriptional regulating cyclin D1 and c-myc in rhabdomyosarcoma and cyclin A1 in breast cancer in vitro." (PMID 27821176, 2016). "Analogous to previous studies in colon cancer showing direct interaction of VDR and β-catenin, we found that active β-catenin had significantly less interaction with the cyclin D1 promoter after 1,25D3 treatment in mammary tumor cells." (PMID 26008979, 2015). "In human breast cancer cells, curcumin was found to effectively inhibit the expression of several Wnt/β-catenin pathway components such as disheveled, beta-catenin, cyclin D1, and slug in both MCF-7 and MDA-MB-231 breast cancer cell lines." (PMID 25665066, 2015). "Cyclin D1 is an important downsteam gene of Tgfβ and PTHrP in osteogenesis, and similar a connection was observed in breast cancer." (PMID 26404249, 2015). "Consistently, cyclin D1 protein expression was also disrupted in the si-SPRY4-IT1-transfected breast cancer cells compared with the control cells." (PMID 25742952, 2015). "CCND1 most specifically represented the most common focal amplification in the breast cancer patients analysed, 12/28 (43%)." (PMID 25889064, 2015). "Cyclin D1 amplification (CCND1) gene is seen in approximately 15–20% of breast cancers, and persists after the development of metastases." (PMID 26726315, 2015). "Cyclin D1 overexpression is seen in ≥ 50% of breast cancers, but this is of uncertain prognostic relevance." (PMID 26726315, 2015).